TLR4 (toll like receptor 4)
Diseases named in the same sentence as TLR4 in open-access papers (continued):
Sharing a sentence is not in itself a finding about the gene and the disease.
endometritis (continued). "Nucleotide sequence variations between healthy and endometritis-affected cows were revealed using PCR-DNA sequencing for immune (TLR4, TLR7, TNF-α, IL10, NCF4, and LITAF), antioxidant (ATOX1, GST, and OXSR1), and erythritol-related (TKT, RPIA, and AMPD1) genes." (PMID 37368756, 2023). "Additionally, we also validated the function of TLR4 in LPS-induced endometritis immuniohistochemistry." (PMID 36142129, 2022). "Recent studies on the underlying molecular mechanism of Se immunomodulatory action against LPS‐induced endometritis in rats have revealed that Se hampered TLR‐4 migration to lipid rafts by bringing modification in lipid rafts through cholesterol depletion via LxRα‐ABCA1 pathway regulation." (PMID 36348775, 2022). "We hypothesized that Bta-miR-24-3p has an immunomodulatory effect on LPS-induced endometritis through TLR4/NF-ĸB signaling pathway targeting LGALS9." (PMID 34943807, 2021). "Our results also showed an increased level of TLR4 during endometritis." (PMID 31756048, 2020). "In this context, to further evaluate the potential molecular mechanism by which C. butyricum suppresses the production of pro-inflammatory factors, we hypothesized that C. butyricum could alleviate endometritis by suppressing the TLR4/NF-κB signaling pathway and HDAC levels." (PMID 36321897, 2022). "In addition, suppression of LPS-induced activation of p38 and JNK by AS IV suggests that AS IV alleviation of LPS-induced endometritis may be achieved by blocking the TLR4-mediated p38 and JNK signaling pathways." (PMID 30669661, 2019). "However, during uterine infection, TLR4 cross-talk with the IL6R pathway may perturb this balance and these concepts need to be explored further." (PMID 26813342, 2016). "Endometritis is characterized by the high expression of CD14, TLR4, IL-1α, IL1-β, IL-6, IL-8, and TNF-α in uterine tissue and cervical mucus." (PMID 39858163, 2025). "However, whether C.t affected the TLR4/NF-κB pathway in endometritis remains unclear." (PMID 38816643, 2024). "TLR4, IL-8, IL-17, NFKB, SLCA11A1, NCF4, Keap1, HMOX1, OXSR1, ST1P1, and SERP1 were manifestly expressed at much higher levels in the buffaloes with endometritis." (PMID 39195794, 2024). "Our results indicated that TLR4, p-p65/p65, and p-IKB/IKB levels were downregulated by C.t in S. aureus-induced endometritis mice, suggesting that C.t inactivates the S. aureus-induced TLR4/NF-κB pathway." (PMID 38816643, 2024). "The expression levels of the genes TLR4, TLR7, TNF-α, NCF4, LITAF, OXSR1, TKT, RPIA, and AMPD1 were significantly greater in endometritis-affected Holstein dairy cows than in resistant ones." (PMID 37368756, 2023). "Using PCR-DNA sequencing for the immunological (TLR4, IL10, TLR7, NCF4, TNF-α, and LITAF) genes, there were changes in the nucleotide sequence between endometritis-affected cows and healthy ones." (PMID 37756095, 2023). "Furthermore, overexpression of ISG15 decreased p65 phosphorylation and nucleation, while interference with ISG15 expression had the opposite effect, suggesting that ISG15 may play a role in alleviating inflammation by inhibition of the TLR4/NF-κB signaling pathway in LPS-induced endometritis." (PMID 34573559, 2021). "The levels of the PRLR, LTF, CLA-DRB3.2, beta defensin, TLR2, TLR4, and CCL5 genes were significantly up-regulated in postparturient goats with endometritis compared to tolerant ones, while the GPX4, GST, SOD3, CAT, and ATOX1 gene patterns demonstrated the opposite tendency." (PMID 39195794, 2024). "Clinical samples analysis revealed that the diversity and abundance of microbiota were altered in patients with endometritis having positive CD138 levels, while mechanistic investigations revealed C.t alleviated S. aureus-induced endometritis by inactivating TLR4/NF-κB pathway." (PMID 38816643, 2024). "SNPs in the TLR4 and TLR2 genes and endometritis tolerance in buffalo have been elaborated." (PMID 37368756, 2023).
endometritis (continued). "Molecular genetic analyses of the immunological (TLR4, TLR7, TNF-α, IL10, NCF4, and LITAF), antioxidant (ATOX1, GST, and OXSR1), and erythritol-related (TKT, RPIA, and AMPD1) genes comparing healthy and endometritis cows found differences in nucleotide sequence and transcript levels." (PMID 37368756, 2023). "The immune (TLR4, TLR7, TNF-α, IL10, NCF4, and LITAF), antioxidant (ATOX1, GST, and OXSR1), and erythritol-related (TKT, RPIA, and AMPD1) genes in endometritis-affected and healthy Holstein dairy cows were characterized in this research using a PCR-DNA sequencing technique." (PMID 37368756, 2023). "Single nucleotide variants (SNPs) in the genes were discovered using PCR-DNA sequencing for immune (TLR4, TLR7, TNF-α, IL10, NCF4, and LITAF), antioxidant (ATOX1, GST, and OXSR1), and erythritol-related (TKT, RPIA, and AMPD1) genes found in resistant and endometritis-infected Holstein dairy cows." (PMID 37368756, 2023). "However, the anti-inflammatory properties of GnRb1 in lipopolysaccharide (LPS)-challenged endometritis through the TLR4-mediated NF-κB signaling pathway has not yet been researched." (PMID 34885671, 2021).
intracerebral hemorrhage (39 papers, 2012 to 2025). A cerebrovascular disorder characterized by bleeding into one or both cerebral hemispheres including the basal ganglia and the cerebral cortex. "One cause is the inflammatory activation of the Toll-like receptor 4/myeloid differentiation factor (TLR4/MyD88)-signaling pathway after intracerebral hemorrhage." (PMID 35481263, 2022). "While other groups have implicated microglia and heme in the pathogenesis of intracerebral hemorrhage and shown that TLR4−/− was protective, the downstream mediators of TLR4 were never examined with respect to cytokine production or vasospasm." (PMID 23849248, 2013). "Similarly, TLR4-deficient mice have been observed to have reduced ischemic damage, and a TLR4 antagonist is able to reduce neuroinflammation and neurological deficits after intracerebral haemorrhage." (PMID 35269587, 2022). "The expression of TLR4 is significantly increased with the infiltration of inflammatory cells around the hematoma within a few hours after intracerebral hemorrhage." (PMID 38459276, 2025). "Heme is a component of CFH and previous studies have shown that TLR4 is important for the injurious effect of heme in the models of hemolysis, intracerebral hemorrhage, sickle cell disease, and in a trauma/transfusion model of lung injury." (PMID 37991487, 2024). "Meanwhile, intracerebral injection of TLR4 inhibitor decreased the hyperpermeability of BBB in adult mice exposed to intracerebral hemorrhage, while the opposite result was observed after TLR4 overexpression." (PMID 37051251, 2023). "Mechanistically, RA downregulated the TLR4-mediated pro-inflammatory effectors, reduced infiltration of microglia in peri-intracerebral hemorrhage and inhibited apoptosis of neurons co-cultured with activated microglia." (PMID 35928716, 2022). "TLR4-induced autophagy, however, inhibits microglial activation and worsens inflammatory injury in intracerebral hemorrhage." (PMID 35481263, 2022). "The contribution of TLR4 in intracerebral hemorrhage (ICH)-induced brain injury and inflammation has been documented, and a recent study showed that endothelial TLR4 activation by its canonical ligand LPS accelerates cerebral cavernous malformations (CCM)." (PMID 29510725, 2018). "In conclusion, our findings reveal that heme triggers TLR4-mediated inflammatory injury via the MyD88/TRIF signaling pathway in intracerebral hemorrhage in mouse brain." (PMID 22394415, 2012). "TLR4 is also implicated in heme-mediated microglia activation followed by NFKB activation, increasing pro-inflammatory cytokine expression and inflammatory injury after intracerebral hemorrhage." (PMID 33374506, 2020). "Recent studies showed that PCB could significantly mitigate neuroinflammation through inhibiting TLR4 signaling pathway and M1-like microglial polarization in an intracerebral hemorrhage and traumatic brain injury model." (PMID 29850586, 2018). "Others have also shown that a TLR4 antagonist limits damage from intracerebral hemorrhage." (PMID 30319361, 2018). "TLR4-induced autophagy contributes to microglial activation and inflammatory injury and might provide novel therapeutic interventions for intracerebral haemorrhage (ICH)." (PMID 26872020, 2016). "In addition, emerging studies revealed that TLR4 is a sensor for autophagy, and TLR4-mediated activation of autophagy contributes to microglial activation and pro-inflammatory injury in intracerebral haemorrhage." (PMID 26872020, 2016). "Additionally, in a mouse model of intracerebral hemorrhage, Heme interacts with TLR4 receptor, activates TLR4-mediated inflammatory injury through the MyD88/TRIF signaling pathways." (PMID 23967200, 2013). "Accumulated studies showed that TLR4 was upregulated in intracerebral hemorrhage (ICH), and TLR4 mediated inflammation may lead to poor outcome in these individuals." (PMID 24015844, 2013). "TLR4 may be a novel intervention for intracerebral hemorrhage and TBI." (PMID 37528888, 2023).
intracerebral hemorrhage (continued). "Resatorvid, a selective TLR-4 antagonist, has been reported to exert a neuroprotective effect by decreasing inflammation in various experimental models of cerebral injury such as traumatic brain injury, cerebral I/R injury, and intracerebral hemorrhage-induced brain injury." (PMID 29113143, 2017). "However, previous studies suggested that microglia-related effects may relate to Toll-like-Receptor (TLR) activation via cfDNA: inhibition of the TLR4 signaling pathway in intracerebral hemorrhage in mice reduced the amount of M1-like microglial polarization and improved early functional outcomes." (PMID 36928073, 2023). "SsnB is a polyphenolic natural compound that improved intracerebral hemorrhage and endotoxin shock outcomes in mice in a TLR2/TLR4-dependent manner." (PMID 36359764, 2022). "Through the inhibition of the TLR4/NF-κB pathway, the secretion of TNF-α, IL-6, and IL-1β decreases, and the injury to the brain due to intracerebral hemorrhage can be attenuated." (PMID 33133217, 2020). "TLR4-induced inflammation after intracerebral hemorrhage (ICH) stimulates neuronal apoptosis, which is decreased by IL-1β and TNF-α antagonists, while TLR4 knockout markedly increases the survival rate after ICH." (PMID 33374506, 2020). "Moreover, TLR4-specific inhibitors like TAK-242 have shown promise in promoting haematoma absorption and improving neurologic deficits following intracerebral haemorrhage." (PMID 38790263, 2024). "For example, during intracerebral hemorrhage, hemoglobin from the hematoma can activate macrophages via Toll like receptor 2 (TLR2)/Toll like receptor 4(TLR4) heterodimer, which can secrete IL-23 to induce γδ T cells to produce IL-17 to aggravate secondary damage." (PMID 33868300, 2021). "In the development of intracerebral hemorrhages, the expression of Toll-like receptor 4 (TLR4) is enhanced, and this could lead to an increase in the levels of TNF-α, IL-6, and IL-1β through the TLR4/NF-κB pathway, followed by aggravation of brain lesions." (PMID 33133217, 2020). "Although expression of TLR4 was not determined in that report, other studies have shown that expression of TLR4 was increased in neurons, astrocytes, and microglia in intracerebral hemorrhage." (PMID 30538259, 2018).
brain injury (38 papers, 2011 to 2026). Acute and chronic (see also brain INJURIES, CHRONIC) injuries to the brain, including the cerebral hemispheres, CEREBELLUM, and brain STEM. "For instance, toll-like receptor 4 (TLR4)–expressing microglia interact with astrocytes to promote synaptic loss after brain injury, whereas astrocyte-derived thrombospondin-1 supports synaptic recovery, suggesting that reactive astrocytes contribute to synaptic remodeling in TBI." (PMID 41438969, 2025). "In this context, administration of resatorvid, a small molecule considered as inhibitor of TLR4-mediated pathways, has been shown to dramatically attenuate neuronal apoptosis associated to traumatic brain injury, to significantly decrease TNF-α and IL-1 β levels and to improve neurological recovery." (PMID 29438357, 2018). "The present findings have highlighted that TLR4 signaling regulates the expression of hypoxia-induced inflammatory mediators via the NF-κB pathway and is linked to the inflammatory process in neonatal hypoxic brain injury." (PMID 23388509, 2013). "Our narrative review suggests that TLR2 and TLR4 are known to have a larger role in the pathological progression of ischemic brain injury than other TLRs." (PMID 35510663, 2022). "A recent study showed that quercetin reduced oxidative stress and TLR4-mediated inflammation in mice with neonatal hypoxic-ischemic brain injury." (PMID 35223693, 2022). "Increasing evidence has shown that TLR4 signaling plays an important role in SAH-induced brain injuries." (PMID 33919485, 2021). "Progesterone administration has been shown to modulate the inflammation upregulated by TLR4 and downstream signaling pathways during ischemic stroke and traumatic brain injury." (PMID 33919485, 2021). "We have therefore investigated the role played by TLR4 signaling pathway in the development of mechanisms of secondary inflammatory process in traumatic brain injury (TBI) differ in mice that lack a functional TLR4 signaling pathway." (PMID 23555560, 2013). "In addition, a previous study reported that TLR4-knockdown attenuates brain damage via inhibiting inflammation and autophagy in traumatic brain injury rats." (PMID 36879557, 2023). "Also, neuronal TLR4 activation induces AMPA currents leading to neuronal hyperexcitability during brain injuries and AMPA currents are mediated by glutaminergic neurotransmission." (PMID 37197666, 2023). "A study has shown that the activation of SIRT1 could be responsible for inhibition of TLR4/MyD88/NF-κB signaling pathway thereby reducing neuroinflammation in HINS-induced brain injury." (PMID 35223693, 2022). "Interestingly, down-regulation of the high-mobility group box 1 (HMGB1)/TLR4 pathway is believed to be responsible for functional recovery in rodents with brain injury following MSCs-derived exosome transplantation." (PMID 35986375, 2022). "Inflammation is one of the hallmarks of hypoxic ischemic encephalopathy and experimental studies suggest that the absence of either TLR2 or TLR4 is associated with protection against ischemic brain injury." (PMID 31369614, 2019). "Besides, VEGI attenuates the inflammatory injury and disruption of the BBB through suppressing the TLR4/NF-κB signaling pathway in animals with traumatic brain injury." (PMID 28404943, 2017). "Our study demonstrates that galectin-3 could be working as an endogenous ligand for TLR4 24 h after brain trauma, at a time post-injury when galectin-3 mRNA and protein levels are high." (PMID 28128358, 2017). "Overall, we conclude that galectin-3 acts as an alarmin under conditions of brain trauma, and induces a strong proinflammatory response, most likely through TLR4 activation, and might be involved also in the phagocytic response." (PMID 28128358, 2017).
brain injury (continued). "TLR4/MyD88 signalling is important for the development of post-operative- and post-traumatic brain injury-induced cognitive dysfunction in rats and mice, and glial modulators are currently being trialled for the potential to attenuate post-operative cognitive dysfunction." (PMID 26332828, 2015). "Indeed, TLR4 protein expression was significantly increased at six hours after brain trauma and remained high at 72 hours compared with the levels observed in the control group in our study, which is consistent with the report of Chen and colleagues." (PMID 24669820, 2014). "Moreover, PACAP has been shown to inhibit TLR-4 activation during experimental traumatic brain injury." (PMID 25238233, 2014). "Similarly, a previous study revealed that TLR-4 knockout mice had significantly smaller infarct volumes and better neurological functions than wild-type mice after ischemia- and reperfusion-induced brain injury." (PMID 35454994, 2022). "This hypothesis is supported by a previous report that TLR4 genetic ablation reduces tissues injury events associated with brain trauma and by our data indicating that 7-day treatment with TAK-242, a specific inhibitor of TLR4, significantly improved endothelial function in TBI mice." (PMID 30704505, 2019). "Taken together, the data suggested that brain trauma triggered the inflammatory response mediated by TLR4 cascade in the hippocampus, and EA treatment mitigated the inflammation through downregulation of inflammatory cytokines, which might be helpful to posttraumatic neurogenesis." (PMID 28848607, 2017). "Our results clearly demonstrated that absence of TLR4 reduces the development of neuroinflammation, tissues injury events associated with brain trauma and may play a neuroprotective role in TBI in mice." (PMID 23555560, 2013). "Our previous study concerning brain trauma has shown that progesterone could regulate toll-like receptor 4 (TLR4) and nuclear factor-kappa B (NF-κB) signaling pathway in the brain, which also has been proved to play important roles in early brain injury (EBI) after subarachnoid hemorrhage (SAH)." (PMID 21403869, 2011). "Exosomes derived from umbilical cord mesenchymal stem cells can interfere with the Toll-like receptor 4 (TLR4) signaling of BV-2 microglia, which contributes to reducing neuroinflammation induced by microglia in perinatal brain injury." (PMID 36429051, 2022). "TLR4 is an important member of the TLR family, and high expression of TLR4 has been observed in the tissue around brain trauma." (PMID 28713327, 2017). "In this condition, the recruitment of the immune cells to the ischemic zone in association with pathological mediators, such as oxidative stress, excitotoxicity, MMPs, HMGB1, TLR4, arachidonic acid metabolites, and MAPK, might spread ischemic brain injury." (PMID 35986375, 2022). "That is, TLR4 and C5aR1 represent an alternative upstream regulator in activating NF-κB by inhibiting cAMP/PKA signals and participate in TNF-α, IL-1β, and IL-6 production in MCAO/R-induced brain injury." (PMID 33633530, 2021). "Similarly, toll-like receptor 4 is important in neutrophil entry into brain after ICH and toll-like receptor 4 knockout mice have reduced neutrophil extravasation and reduced ICH-induced brain injury." (PMID 25120903, 2014). "Toll-like receptor 4 (TLR4) is expressed in various cell types and exerts maximal inflammatory responses among the TLR family, which may be an important therapeutic target for patients with post-SAH brain injuries." (PMID 36333751, 2022).